NEAT1 (nuclear paraspeckle assembly transcript 1)
Diseases named in the same sentence as NEAT1 in open-access papers (continued):
Sharing a sentence is not in itself a finding about the gene and the disease.
cancer (continued). "Due to its potential involvement in the beginning and advancement of cancer, as well as the fact that its aberrant expression is associated with clinical aspects such as metastasis, treatment resistance, and patient survival, NEAT1 exhibits characteristics of a tumor driver." (PMID 39337410, 2024). "Finally, to test their relevance in human cancer patients, we asked whether the presence of a NEAT1 mutation correlates with survival." (PMID 37291246, 2023). "Moreover, AUF1 interacts with and destabilizes the cancer-associated lncRNA NEAT1." (PMID 32967226, 2020). "However, interpretation of reported results is rather difficult because NEAT1 is upregulated in some cases and downregulated in others even in the same cancer types, and the high expression of NEAT1 is associated with poor prognosis in some studies and good prognosis in others." (PMID 30355755, 2018). "Interestingly, novel functions, such as cell cycle and DNA damage response, suggest that NEAT1 lncRNA may be associated with the parthenogenesis of cancer." (PMID 25815337, 2015). "For instance, it identifies NEAT1-related SNV–ceRNA events as potential targets by linking them to cancer hallmarks (e.g. genomic instability) and drug sensitivity (e.g. NEAT1 enhancing HGSOC’s response to Olaparib)." (PMID 41099605, 2026). "Consistent with previous results, NEAT1‐31 promoted the elimination of multiple cancer cell types and prolonged overall survival." (PMID 40344649, 2025). "Beyond their roles in transcriptional control, both NEAT1 and MALAT1 have also been implicated in ferroptosis and drug resistance regulation across multiple cancer types." (PMID 41294881, 2025). "In fibroblasts cocultured with endothelial cells, we observed significant upregulation of genes associated with cancer progression (MALAT1, NEAT1), vascular endothelial growth factor (VEGFA), and proinflammatory cytokines (NCOA3, IRF1)." (PMID 39805002, 2025). "NEAT1‐31 was removed, different macrophages were co‐incubated with the cancer cells, and phagocytosis was measured using a flow‐based phagocytosis assay." (PMID 40344649, 2025). "Nuclear enriched abundant transcript 1 (NEAT1), a long noncoding RNA (lncRNA) gene, has been demonstrated to play a key role in cancer development." (PMID 41323778, 2025). "These regulatory molecules have demonstrated significant roles in cancer progression: NEAT1 functions as an oncogenic lncRNA in multiple malignancies, while KCNQ1OT1 serves as a tumor promoter through various mechanisms." (PMID 41378121, 2025). "Building on reports that NEAT1 interacts with DNMT1 in cancer models, we investigated this axis in LN." (PMID 41457558, 2025). "One notable mechanism involving writers consists of m6A-methylation of lncRNA that is overexpressed in cancer, such as NEAT1, which is overexpressed in many cancers." (PMID 40243425, 2025). "NEAT1, known as nuclear‐enriched abundant transcript 1, functions as a mediation factor for transcription and is overexpressed in several types of cancer." (PMID 40259205, 2025). "Marker genes that were highly expressed in this group of cells include the cancer-associated imprinted genes XIST, NEAT1, and MEG3." (PMID 40585258, 2025). "Overall, NEAT1 is a lncRNA of considerable interest across multiple cancer types, adjacent to this are its unique and context-dependent functions, including critical roles in innate immune regulation and paraspeckle formation." (PMID 40521240, 2025). "Long non-coding RNA NEAT1 was identified as a cancer biomarker and has been found to play significant roles in a few various cancers." (PMID 41457558, 2025). "The nuclear paraspeckle assembly transcript 1 (NEAT1) is another lncRNA with a diverse abundance of roles in cancer." (PMID 40521240, 2025). "Beyond traditional tumor markers, the long non-coding RNA (lncRNA) NEAT1 is abnormally expressed in many malignant tumors and is a significant indicator of poor prognosis." (PMID 40486880, 2025).
cancer (continued). "The long noncoding RNA (lncRNA) nuclear paraspeckle assembly transcript 1 (NEAT1) has 29.5 pUG repeats and is overexpressed in many cancers." (PMID 40682817, 2025). "LincNEAT1 Encoded‐NEAT1‐31 micropeptide directly binds with Aurora‐A and enhanced AKT pathways to pormotes phagocytosis against multi cancer cells." (PMID 40344649, 2025). "The PC cases were categorized using T staging in order to assess the association between serum levels of NEAT1, miR-129-5p, and their related targets BCL2 and TGF-β1 with cancer progression." (PMID 40730640, 2025). "This review consolidates the latest findings about the role of lncRNA NEAT1 in stress response and immune cell function in non-cancer diseases." (PMID 40362651, 2025). "NEAT1 (nuclear paraspeckle assembly transcript 1) is a lengthy, non-coding RNA that profoundly influences the adaptability of cancer cells." (PMID 41013839, 2025). "The results indicated that AT‐macrophages were particularly enriched with NEAT1‐31 across the various cancers." (PMID 40344649, 2025). "The results revealed that the application of the NEAT1‐31 peptide dramatically enhanced the phagocytosis of multiple cancer cell‐types." (PMID 40344649, 2025). "In recent years, mounting evidence has demonstrated the role of lncRNA NEAT1 in immune-related diseases, in addition to cancers." (PMID 40362651, 2025). "The role of Neat1 in regulating cancer immune cells infiltration and activation remains controversial." (PMID 40527978, 2025). "This restricts NEAT1‐31 to promoting the phagocytic function of only those macrophages that have recognized cancer cells." (PMID 40344649, 2025). "Our analysis identified numerous SIR-associated mutations in oncogenes (e.g., MECOM, NFATC2) and tumor suppressor genes (e.g., LRP1B, PTPRD), as well as in cancer-associated lncRNAs (e.g., MALAT1, NEAT1)." (PMID 41153425, 2025). "Through its interaction with components of these pathways, NEAT1 not only affects cancer progression but also modulates essential processes associated with cellular plasticity, thereby underscoring its importance in cancer biology." (PMID 41013839, 2025). "It has been reported that the elevation of NEAT1 in cancer cells promotes cell growth, migration, and invasion and inhibits cell apoptosis." (PMID 39184920, 2024). "Nuclear paraspeckle assembly transcript 1 (NEAT1) is elevated in several types of cancer and promotes cancer growth." (PMID 39409111, 2024). "Of functional significance, we find that the MUC1-C/NEAT1 pathway is of importance for the cancer stem cell (CSC) state and anti-cancer drug resistance." (PMID 38802648, 2024). "The present results uncover a previously unrecognized role for MUC1-C in integrating activation of the inflammatory NF-κB pathway with driving expression of the NEAT1 gene in cancer cells." (PMID 38802648, 2024). "This means that NEAT1 can control the growth, proliferation, adhesion, and development of cancer cells by blocking miR-506." (PMID 39337410, 2024). "NEAT1 propels the advancement of cancer by spurring cell proliferation, EMT, invasion, and metastasis, and it instigates resistance to chemotherapy in TNBC cells." (PMID 39286016, 2024). "NEAT1 can promote the efflux of chemotherapeutic drugs by regulating the expression and activity of ABC transporters in cancer cells, thereby causing cancer chemotherapy resistance." (PMID 38970092, 2024). "NEAT1 promotes chemotherapeutic resistance in cancer mainly by enhancing the homologous recombination ability of cancer cells." (PMID 38970092, 2024). "NEAT1 can also affect CSCs by activating the signaling pathway to induce chemoresistance of cancer cells." (PMID 38970092, 2024). "NEAT1 has different expression patterns in different cancers and can affect the occurrence, development and metastasis of many cancers by acting as oncogenes or oncogenes, and is a potential diagnostic and therapeutic target for cancer." (PMID 38970092, 2024).
cancer (continued). "NEAT1 can inhibit apoptosis and promote chemotherapy resistance of cancer by regulating the expression of key apoptosis-related factors in the mitochondrial apoptosis pathway." (PMID 38970092, 2024). "The present results demonstrate that MUC1-C is necessary for NEAT1 expression in human cancer cells by NF-κB- and MYC-mediated pathways." (PMID 38802648, 2024). "In NSCLC, NEAT1 was pivotal in regulating ferroptosis sensitivity, influencing cancer cell fate (Wu and Liu, 2021)." (PMID 38343745, 2024). "In line with their integration in promoting cancer, our results further demonstrate that MUC1-C and NEAT1 regulate common sets of genes associated with chronic inflammation, induction of EMT and activation of the NOTCH1/2 stemness factors." (PMID 38802648, 2024). "The mTOR inhibitor Rapamycin was shown to exert its anti-cancer effect by perturbing this mTOR/NEAT1-mediated mechanism." (PMID 38203767, 2024). "In NSCLC, NEAT1 functions as an oncogenic lncRNA, showcasing robust expression within cancer tissues." (PMID 38343745, 2024). "At present, NEAT1 has been shown to be able to regulate biological functions of cancer cells by interacting with mRNA, DNA and proteins." (PMID 38970092, 2024). "NEAT1, an oncogenic lncRNA, induces cell proliferation, metastasis, invasion, and therapy resistance, while suppresses apoptosis in cancer cells." (PMID 39401197, 2024). "In a variety of cancers, NEAT1 can enhance stem cell characteristics and mediate an oncogenic phenotype." (PMID 39337410, 2024). "When it comes to a number of different kinds of cancer, NEAT1 is frequently increased, and the levels of expression are related to the illness’s severity." (PMID 39512820, 2024). "MUC1-C promotes resistance of cancer cells to cytotoxic and targeted agents; whereas less is known regarding involvement of NEAT1 in the drug-resistant phenotype." (PMID 38802648, 2024). "NEAT1 induces cancer cell resistance to chemotherapeutic drugs by regulating cell apoptosis, cell cycle, drug transport and metabolism, DNA damage repair, EMT, autophagy, cancer stem cell characteristics, and metabolic reprogramming." (PMID 38970092, 2024). "NEAT1 can induce chemoresistance in cancer cells by regulating the expression of these stemness factors." (PMID 38970092, 2024). "We identified several non-coding lncRNAs, particularly noting that two of them (NEAT1 and MALAT) have existing precedents associated with chemo-resistance in cancer." (PMID 38612643, 2024). "The role of NEAT1 in chemotherapy resistance of human cancer involves a variety of mechanisms, including inhibition of apoptotic pathways, increased ATP-driven drug efflux, enhanced DNA damage repair, and induction of autophagy." (PMID 38970092, 2024). "In OC, NEAT1 is more highly expressed in cancers than in normal tissues, and it facilitates tumorigenesis and progression, high expression of NEAT1 is correlated with unfavorable prognosis." (PMID 38898019, 2024). "Given the importance of metabolic reprogramming in cancer metastasis and progression, we further explored the impact of NEAT1 on the regulation of aerobic glycolysis and oxidative phosphorylation." (PMID 38733179, 2024). "As a notable molecular sponge, NEAT1 competes with various miRNAs to regulate oncogenic components within cancer." (PMID 38343745, 2024). "NEAT1 is an abundantly expressed lncRNA widely studied in cancer progression, tumor cell migration, invasion, metastasis, and epithelial-to-mesenchymal transition." (PMID 38474419, 2024). "The inhibition of NEAT1 has been shown to deplete the reservoir of cancer stem cells endowed with robust self-renewal and multi-lineage differentiation capabilities, underscoring NEAT1’s cardinal role in the regulation of tumor stemness." (PMID 39286016, 2024).
cancer (continued). "Based on previous studies, paraspeckles are a type of subnuclear body built on the lncRNA NEAT1 that is involved in diverse physiological processes, including cell differentiation, stress responses, neurodegeneration, and cancer progression." (PMID 38898019, 2024). "NEAT1 increases the growth and invasion of cancer cells via binding to the human antigen R (HuR) protein and sponging miR-124-3p." (PMID 39337410, 2024). "NEAT1's involvement in regulatory networks, including its interactions with other molecules, shapes cancer cell behavior." (PMID 38343745, 2024). "A recent study, however, unravels an opposite role of NEAT1, mainly its long isoform NEAT1v2/NEAT1_2, which is regulating cancer cell metabolism." (PMID 38203767, 2024). "Many studies have been conducted to explore the interrelation between NEAT1 and resistance to chemotherapy or radiotherapy across diverse cancer types." (PMID 38343745, 2024). "NEAT1 can affect the chemoresistance of cancer cells by regulating the GO/G1 phase of the cell cycle." (PMID 38970092, 2024). "The long noncoding RNA nuclear paraspeckle assembly transcript 1 (NEAT1) is involved in a variety of human cancers." (PMID 39032650, 2024). "We also found that the MUC1-C/XIST pathway regulates expression of the NEAT1 and MALAT1 lncRNAs, which have been linked to inflammation and cancer progression." (PMID 38740827, 2024). "In DLBCL, c-MYC has been implicated in the transcriptional activation of the lncRNAs NEAT1 and FIRRE, which facilitate cancer cell proliferation." (PMID 38886753, 2024). "NEAT1, an extensive lncRNA, demonstrates notable expression across various cancer types, including LCs." (PMID 38343745, 2024). "Of note, recent studies have also demonstrated that the knockdown of NEAT1 can inhibit cancer cells’ proliferation, movement, and infiltration while enhancing apoptosis." (PMID 39409111, 2024). "Collectively, NEAT1 emerges as a pivotal player in the promotion of cell proliferation within diverse cancer categories." (PMID 38343745, 2024). "Nevertheless, comprehensive research efforts are necessary to gain a more profound comprehension of NEAT1's specific contributions to apoptosis and cell cycle regulation in the context of cancer." (PMID 38343745, 2024). "Recent studies have shown that NEAT1 is positively correlated with the HR-related proteins RAD51 and FOXM1 in OC, and that knockdown of NEAT1 sensitizes cancer cells to platinum-based chemotherapeutic agents by inhibiting the HR process." (PMID 38970092, 2024). "Similar results were obtained in MDA-MB-468 TNBC, MDA-MB-436 TNBC and DU-145 CRPC cells, indicating that MUC1-C-dependent NEAT1 expression is observed across cancer cell lineages." (PMID 38802648, 2024). "The lncRNA nuclear paraspeckle assembly transcript 1 (NEAT1) has been extensively studied and reported to be dysregulated in a variety of brain disorders and cancers." (PMID 39032650, 2024). "As reported for MUC1-C, silencing NEAT1 was associated with suppressing the BENPORATH ES gene signature, derived from embryonic stem cells and advanced carcinomas." (PMID 38802648, 2024). "NEAT1 shows typical features of tumor drivers because it can be involved in cancer initiation and progression, and its abnormal expression is associated with clinical characteristics including metastasis, therapy resistance, and patient survival." (PMID 37310654, 2023). "Despite being upregulated in a variety of human cancer types and having clear oncogenic roles in solid tumors, prognostic analysis of the short isoform NEAT1 (NEAT1_1) revealed that high expression is positively correlated with OS of AML patients." (PMID 37267628, 2023). "NEAT1 has also been shown to regulate aerobic glycolysis to affect tumor immunosurveillance by T cells in this type of cancer." (PMID 37025585, 2023). "Among them, SNHG4 and NEAT1 drew our attention for their complex biological functions in cancer regulation." (PMID 37596700, 2023).
cancer (continued). "Another layer of regulation involves HIF-2α, which enhances NEAT1 expression, subsequently influencing the epithelial-mesenchymal transition, a critical process in cancer metastasis." (PMID 37759495, 2023). "Three of the lncRNAs include HOX transcript antisense intergenic RNA (HOTAIR), OIP5-AS1 and nuclear paraspeckle assembly transcript 1 (NEAT1) are highly expressed in different cancer cells compared to adjacent normal tissues." (PMID 37127605, 2023). "In cancer research, nuclear paraspeckle assembly transcript 1 (NEAT1), a nuclear-enriched lncRNA, appears to be overexpressed in various cancerous tissues, and the dysregulation of NEAT1 contributed to cancer progression and metastasis." (PMID 36824662, 2023). "As one of the best-studied oncogenic lncRNAs, nuclear paraspeckle assembly transcript 1 (NEAT1) is known to promote metastasis of various cancers, including those of the breast, lung, thyroid gland, colon, ovary, prostate, and liver." (PMID 37407839, 2023). "Some of the imprinted lncRNAs responsible for cancer initiation and development have been identified; these include NEAT1, MALAT1, Xist, and ZEB1-AS1." (PMID 36864364, 2023). "NEAT1 by blocking miR-138-5p enhanced the proliferation, migration, and invasion of cancer cells, and inhibited apoptosis." (PMID 37310654, 2023). "It has been reported that in cancer development, lncRNA NEAT1 binds to miRNAs as a competing endogenous RNA (ceRNA), thus affects the expression levels of their target genes." (PMID 37752791, 2023). "YTHDF2 promotes the degradation of LncRNA NEAT1 by selectively recognizing the M6A modification on NEAT1 and thus exerts anti-cancer effects." (PMID 37865763, 2023). "NEAT1 expression translationally modulated NAD(P)H: quinone oxidoreductase 1 expression in radiation-resistant cancer cells." (PMID 37310654, 2023). "In contrast, miR-133b silencing or NEAT1 overexpression repressed the inhibitory effects on migratory and invasive capacity of cancer cells." (PMID 37310654, 2023). "For example, high levels of m6A NEAT1 correlate with bone metastasis and the overexpression of this lncRNA induce cancer cell metastasis in mouse model through an m6A-dependent mechanism." (PMID 36969033, 2023). "In the present study, we have identified a previously unreported contribution of the lncRNA, NEAT1, to cancer cell proliferation via VIRMA-mediated m6A methylation." (PMID 37208522, 2023). "A few lncRNAs in this list, notably MALAT1 and NEAT1, have been studied for their regulatory roles in cancer progression." (PMID 37628839, 2023). "NEAT1 was found upregulated in superclusters A and B compared to cluster C. NEAT1 has been described as promoting chemoresistance and cancer stemness." (PMID 38066300, 2023). "NEAT1 is one of the main cancer-related lncRNAs, overexpressed in several types of tumors and correlated to a worse patients survival." (PMID 36969033, 2023). "NEAT1 binds to miR-202 and inhibits its tumor-suppressive character, thus driving cancer progression." (PMID 37175800, 2023). "In this context, a study delved into the functional aspects of NEAT1 in MB and found its role as sponge for miR-23a-3p, a miRNA recognized as a tumor suppressor that is frequently downregulated in various cancers." (PMID 37835380, 2023). "It is indicated that the stability of NEAT1 in cancer cells is weakened by ROS stresses, which is one of the reasons for the decreased NEAT1 expression in senescent cancer cells." (PMID 37752791, 2023). "NEAT1 is highly expressed across tissues and frequently overexpressed in human tumors, which correlates with worse survival rate in cancer patients." (PMID 37444543, 2023). "In HCC, overexpression of NEAT1 promotes tumour progression and metastasis, and maintains the properties of cancer stem cells." (PMID 37752791, 2023). "Nuclear enriched autosomal transcript 1 (NEAT1) is a newly discovered lncRNA that plays functional role in cancer carcinogenesis." (PMID 37310654, 2023).